CD68 (CD68 molecule)
Diseases named in the same sentence as CD68 in open-access papers (continued):
Sharing a sentence is not in itself a finding about the gene and the disease.
oropharyngeal squamous cell carcinoma (5 papers, 2017 to 2022). "Finally, the density of CD68+ macrophages appears to be higher in the tumor area (but not in the stromal regions) of HPV-positive oropharyngeal squamous cell carcinomas (OPSCCs) than in HPV-negative OPSCCs." (PMID 29541395, 2018).
pancreatitis (5 papers, 2017 to 2023). Inflammation of the pancreas. "To evaluate the local pancreatic immune response during pancreatitis, we labelled tissue sections with CD68 and CCR2 to identify pancreatic macrophages and infiltrating monocytes." (PMID 37402858, 2023). "Immunohistochemistry results revealed that Ly6G + neutrophils and CD68 + macrophages were abundantly recruited in the caerulein pancreatitis group as compared to the normal control group." (PMID 36229875, 2022). "Indeed, serum GP2 levels are increased in pancreatitis animal models and patients with CD68,69." (PMID 33594081, 2021).
somatotropinomas (5 papers, 2023 to 2025). "T-cells have been reported to dominate the TME across all subtypes of pituitary adenomas, while recent studies have shown that CD68 + macrophages predominate the immune infiltration in somatotropinomas." (PMID 40415137, 2025). "In some studies, CD68 + macrophages and CD8 + T-lymphocytes have been linked to growth patterns of somatotropinomas and response to first-line medical therapy with first-generation somatostatin receptor ligands (SRLs)." (PMID 40415137, 2025). "Specifically, higher CD68 + macrophage infiltration has been correlated with increased tumor volume, higher Ki-67%, and cavernous sinus invasion in somatotropinomas." (PMID 40415137, 2025). "In somatotropinomas, higher amounts of tumor-infiltrating CD68+ macrophages, widely present in sparsely granulated forms, correlated positively with tumor volume and higher expression of Ki-67 and MMPs, cavernous sinus invasion." (PMID 37958702, 2023).
ulcer (5 papers, 2012 to 2022). "It has been reported that CD68-positive macrophages are one of the main inflammatory cells relevant to the pathogenesis of ulcers." (PMID 33224991, 2020). "Interestingly, we found a direct correlation between the frequency of CD68+ cells and number of amastigotes and there was an association between macrophages number and the area of necrosis in both E-CL and L-CL and between majority and size of the ulcer and CL." (PMID 28115669, 2017). "High levels of CD68 macrophages in the dermis and wound edges in chronic leg ulcers have previously been detected yet, as in our pre-ESWT ulcer biopsies, levels of macrophage activation markers remained generally low, suggesting potential senescence." (PMID 34360610, 2021). "The authors found that, in nonhealing ulcers examined over a period of 6 weeks, the CD68+Arg1+ population was significantly reduced in comparison with that in healing ulcers." (PMID 35954275, 2022).
viral hepatitis (5 papers, 2013 to 2025). An acute or chronic inflammation of the liver parenchyma caused by viruses. "Moreover, in accordance with our previous study, we found that high proportions of CD38+ cells, as well as CD38+CD68+ cells, were associated with improved responses to ICB, albeit only at a significant level in patients with viral hepatitis." (PMID 37342338, 2023). "CD68+ macrophages are diffusely located in portal and lobular areas in healthy liver tissues but are increased in the portal areas of diseased liver tissues as commonly seen in chronic viral hepatitis." (PMID 37703304, 2023). "Also, the number of CD14+CD68+ Kupffer cells is increased in patients with viral hepatitis in another study." (PMID 29854831, 2018). "CD68 immunostaining revealed macrophage aggregation constituting hCLS in the liver from NAFLD/NASH patients, which was rarely observed in patients with chronic viral hepatitis." (PMID 24349208, 2013). "In the HCV-negative cohort (n = 103): CD68/CD163 ratio maintained significant predictive value for thrombosis (OR = 1.64, 95% CI:1.119–2.404, p = 0.011) in the HCV-negative cohort, confirming the robustness of our findings independent of viral hepatitis status." (PMID 41239536, 2025).
acne (4 papers, 2014 to 2024). An inflammatory process of the sebaceous glands which is characterized by comedones, nodules, papules and/or pustules on the skin. "Previous studies have indicated that papules can form in under 6 hours and exhibit a profound inflammatory response as evidenced by increased levels of CD4 T cells, neutrophils, and CD68+ macrophages in acne biopsies." (PMID 38854033, 2024). "Previous studies have indicated that papules can form in under 6 h and exhibit a profound inflammatory response as evidenced by increased levels of CD4 T cells, neutrophils, and CD68+ macrophages in acne biopsies." (PMID 39143467, 2024). "Number of CD68+ macrophages is significantly higher both in early acne lesions and uninvolved follicles in acne patients compared with healthy subject." (PMID 38357543, 2024). "We defined the markers of T cell subsets at mRNA level and studied Th1 (T-bet), Th17 (IL-17A), Treg (Foxp3) cells, cytotoxic CD8+ T-cells and CD68 macrophages and CD83 positive activated dendritic cells in clinically early acne lesions by immunohistochemistry both phenotypically and proportionally." (PMID 25153527, 2014).
adenomyosis (4 papers, 2018 to 2025). The growth of endometrial tissue inside the muscular wall of the uterine corpus. "Targeting macrophage-related biomarkers, such as specific cytokines (e.g., TNF-α, IL-6) or macrophage surface markers (e.g., CD68), could provide diagnostic tools or therapeutic targets for adenomyosis." (PMID 40989079, 2025).
AIDS (4 papers, 2015 to 2022). A syndrome resulting from the acquired deficiency of cellular immunity caused by the human immunodeficiency virus (HIV). "Antiretroviral treatment with 6-Cl-ddG prevented the appearance of mononuclear infiltrates, mononuclear nodules, and MNGC as detected with IBA-1 and CD68 in SIV/+AIDS." (PMID 27737697, 2016). "To determine whether macrophages were contributing to the pro-inflammatory milieu in the colon of AIDS patients, we performed double labeling of CD68+ macrophages with TNF-α and IL-1β using a dye swap method with validation by fluorescence microscopy." (PMID 26475133, 2015). "TNF-α+ and IL-1β+ CD68-positive macrophages were present in the lamina propria of AIDS patients." (PMID 26475133, 2015). "The microglial/macrophage activation markers CD68 and CD163 were occasionally immunodetected in the cerebellum of the control and SIV/-AIDS macaques." (PMID 27737697, 2016).
Cachexia (4 papers, 2015 to 2025). Severe weight loss, wasting of muscle, loss of appetite, and general debility related to a chronic disease. "In the present study, we describe an increase of the CD68+ myeloid population also in the liver, across the progression of cachexia, which may be the cause for increased IL‐1β protein secretion that can be detected in the circulation." (PMID 37177862, 2023). "Another study showed similar findings in cachectic rodents and humans, demonstrating a progressive increase of CD-68-positive myeloid cells in the liver as cachexia develops." (PMID 39596015, 2024). "In rodent cachexia, we found progressively higher numbers of CD68+ myeloid cells in the liver along cancer‐cachexia development." (PMID 37177862, 2023). "CC presented a higher CD68/Iba1 ratio in the caudate nucleus, what may indicate that cachexia leads towards a microglia profile with increased phagocytic activity (CD68) in relation to the total microglia density (Iba1) in that region." (PMID 39962362, 2025). "The authors found a significant increase in the number of CD-68-positive monocytes associated with increased IL-6 levels, when compared to liver samples from cancer patients without cachexia." (PMID 39596015, 2024). "In the present study, we found a linear increase in the CD68+ myeloid population, paralleling the progression of cachexia, which was endorsed by the finding of increased detection of specific receptors (F4/80 and Cd68) and chemokine (Ccl2) genes of CD68+ population." (PMID 37177862, 2023).
chondrosarcoma (4 papers, 2023 to 2025). A malignant cartilaginous matrix-producing mesenchymal neoplasm arising from the bone and soft tissue. "Furthermore, in a validated cohort of 27 conventional and 49 dedifferentiated chondrosarcomas, a low expression of CD68+ TAMs was identified in approximately 39% of the patients, while its high expression was found in almost 61%." (PMID 37958467, 2023). "In chondrosarcoma, CD68+ CD163+ TAMs are the main immune population, and a high CD68+/CD8+ ratio independently forecasts metastatic presentation and poor prognosis." (PMID 40469285, 2025). "Here, we observed a gCAF subcluster (CD68, HLA-DPB1, and CFD) in conventional central chondrosarcoma, which was characterised by granulocyte activation." (PMID 38267611, 2024).
chordoma (4 papers, 2020 to 2023). Chordomas are rare malignant tumors arising from embryonic remnants of the notochord in axial skeleton. "We found that macrophages were enriched in primary chordomas, and the results were confirmed by IHC with the macrophage markers CD68 and CD163." (PMID 37784253, 2023). "In this study, CD68+ pan macrophages more significantly infiltrated chordoma tumor parenchyma than stroma, unlike trends appreciated in the T cell compartment, and all myeloid cell types identified were within notably closer proximity to chordoma tumor cells than T cells." (PMID 36338744, 2022). "Finally, several other immune features, such as CD45RA, CD57, CD66b, CD68, and IL17, may also be evaluated for their expression profile in chordoma tissues, as well as for eligibility for inclusion in the immune classifier and nomogram, as they have been shown to be indicative of cancer prognosis." (PMID 32508056, 2020).
Clear Cell Renal Cell Carcinoma (4 papers, 2019 to 2025). "Evaluation of protein expression within histologic sections of primary clear cell renal cell carcinoma patient samples showed intensity of IRF8 by CD68+ macrophages correlated inversely with stage." (PMID 31221219, 2019).
coronary atherosclerosis (4 papers, 2012 to 2024). Atherosclerosis of the coronary vasculature. "In a recent study, epicardial adipose tissue volume has been positively associated with CD68 and inflammatory cytokines, and negatively with adiponectin gene expression, being these associations strongly linked to human coronary atherosclerosis." (PMID 23951013, 2013). "This correlation may further strengthen the ability of NIRF-IVUS to serve as an unbiased tool for the detection of relevant pathophysiological risk criteria of human coronary atherosclerosis, such as the accumulation of CD68-positive inflammatory cells." (PMID 39246665, 2024).
dengue (4 papers, 2011 to 2023). "We also observed increased numbers of CD68+ cells infiltrated in hepatic parenchyma and inside sinusoidal capillaries of dengue cases, evidencing the presence of macrophages with characteristic hypertrophic morphology in these areas." (PMID 37457689, 2023). "Macrophages with replicating virus were identified morphologically, as well as with the cell marker CD68 (fluorescent red), which co-localized with the dengue RNA (fluorescent blue)." (PMID 24736395, 2014). "The quantification analysis revealed a 4-fold increase of lymphocytes in the dengue group when compared to non-dengue samples, whereas the number of CD68+ was not statistically different from the controls." (PMID 28006034, 2016). "The quantification of CD68+ cells revealed an 8-fold increment of this population in dengue cases when compared to non-dengue patients." (PMID 28006034, 2016).
follicular lymphoma (4 papers, 2019 to 2024). Follicular lymphoma is a form of non-Hodgkin lymphoma characterized by a proliferation of B cells whose nodular structure of follicular architecture is preserved. "In contrast, in certain tumors like Wilms tumor and follicular lymphoma, high levels of CD68+ macrophages are associated with poor prognosis." (PMID 39531417, 2024). "Follicular lymphoma and CTRL tissue samples were immune stained for CD68, CD163 and tryptase to evaluate total macrophages, M2 macrophages, and mast cells, respectively." (PMID 35268349, 2022). "We show here that rituximab exerts beneficial effects, especially in the subgroup of follicular lymphoma patients with low intrafollicular CD3, CD5, CD8, and ZAP70 and high CD56 and CD68 expression." (PMID 31273513, 2019). "Taken together, we show here that rituximab exerts beneficial effects especially in the subgroup of follicular lymphoma patients with low intrafollicular CD3, CD5, ZAP70 and CD8, and high CD56 and CD68 expression." (PMID 31273513, 2019). "Rituximab may overcome immune-dormancy in follicular lymphoma in cases with lower intrafollicular T-cell numbers and higher CD56 and CD68 cell counts." (PMID 31273513, 2019). "Furthermore, a recent meta-analysis revealed that high CD68+ LAM numbers, diffuse patterns of FOXP3+ regulatory T (Treg) cells and PD1+ cells, and high PD-L1 cell numbers are adverse factors leading to early transformation of follicular lymphoma." (PMID 35875135, 2022).
gastritis (4 papers, 2019 to 2025). Inflammation of the stomach. "In this study, both C. sappan and spirulina reduced inflammation severity and decreased CD8+ and CD68+ cell infiltration in an ethanol-induced gastritis model." (PMID 40990731, 2025). "Heparanase staining co-localized with CD68+ macrophage staining, suggesting that heparanase in human gastritis originates also from macrophages." (PMID 34220822, 2021). "Since heparanase facilitated the infiltration of macrophages in H. pylori-infected chronic gastritis, we stained H. pylori-infected human gastritis tissue for CD68 and heparanase." (PMID 34220822, 2021). "B7-H4 Tii and CD8 expression differed significantly in CSG versus CAG, whereas PD-L1 Tii, B7-H3 Tum, B7-H3 Tii, B7-H4 Tii, CD8, and CD68 expression differed significantly between gastritis versus neoplasia." (PMID 30813210, 2019). "To further investigate the role of Jagged1 in macrophage activation during H. pylori infection, we performed immunofluorescence staining of Jagged1 and CD68, a macrophage marker, in the gastric mucosa of H. pylori-negative (H. pylori–) and H. pylori-positive (H. pylori+) gastritis patients." (PMID 34305857, 2021). "Additionally, the infiltration of Jagged1+ CD68+ cells was higher in the gastric mucosa of H. pylori-positive gastritis patients compared with negative controls (NCs)." (PMID 34305857, 2021).
Gliosis (4 papers, 2021 to 2025). Gliosis is the focal proliferation of glial cells in the central nervous system. "Gliosis was measured by Iba-1, CD68, and TSPO, markers for microglia, as well as by the astrocytic marker GFAP." (PMID 34948098, 2021). "Gliosis and retinal microglial activation were measured by using GFAP, CD68, and ITGAM mRNA quantification and GFAP, CD68, and Iba1 immunofluorescence stainings." (PMID 35236378, 2022). "Gliosis was mainly characterised by the presence of reactive astrocytes and by less conspicuous microglial activation, as confirmed by immunohistochemistry for GFAP and CD68, respectively." (PMID 40898647, 2025).
hemangioma (4 papers, 2020 to 2024). A benign vascular lesion characterized by the formation of capillary-sized or cavernous vascular channels. "LCA is sometimes positive for transferrin receptors compared with other hemangiomas, which also shows positive staining for endothelial cells and tissue cells, such as factor VIII(+), CD31(+), CD163(+), CD68(+), and CD21(+)." (PMID 39544335, 2024). "The vessels in hemangioma are (CD31+, CD34+, CD8-), while in littoral cell angioma they are (CD31+, CD34-, CD8-, CD21+, CD68+)." (PMID 37854759, 2023). "In 19 cases, we used additional immunohistochemical stains (CD 31, CD34, PanCK, CD68, S100) to exclude possible differentials including fibrohistiocytic tumors, hemangiomas, and peripheral nerve sheath tumors but the results of these stains turned out to be negative, except for S100 and CD68." (PMID 32343359, 2020). "Both hemangiomas and LCA are positive for CD-31 however hemangioma is negative for CD-68." (PMID 38975436, 2024).
histiocytic neoplasm (4 papers, 2023 to 2025). Histiocytic tumors are a heterogeneous group of tumors and tumorlike masses commonly associated with histologically identical extracranial lesions. "RDD is characterized by excessive tissue infiltration by dendritic cells, macrophages, or monocyte-derived cells, with a histopathologic diagnosis based on the presence of CD68+, CD163+, and S100+ histiocytes, which differentiate it from other histiocytic neoplasms." (PMID 37378192, 2023).
intracerebral hemorrhage (4 papers, 2012 to 2025). A cerebrovascular disorder characterized by bleeding into one or both cerebral hemispheres including the basal ganglia and the cerebral cortex. "Although the presence of GFAP+/CD68+ and MBP+/CD68+ macrophages in the spleen could be related to intracerebral hemorrhage, it raises a provocative hypothesis that brain volumetric loss may be due to clearance of brain parenchymal elements." (PMID 40536810, 2025). "In addition, in vivo, microglial proliferation and CD68 expression induced by intracerebral hemorrhage are greater in older rats than in young adults." (PMID 23300752, 2012). "It has been found that in intracerebral hemorrhage (ICH), microglial activation marker CD68 was co-located with EHD2, a member of the Eps15 homology domain (EH domain) family." (PMID 36712438, 2022). "Macrophages/microglia do not express CD68 in the healthy brain but become CD68-positive after acute ischemic stroke and/or intracerebral hemorrhage." (PMID 30705764, 2019).
intracranial aneurysm (4 papers, 2020 to 2025). "The results showed that CD68 positivity and wall enhancement were significantly associated with intracranial aneurysm wall degeneration, growth, and rupture." (PMID 37744724, 2023). "Specifically, intracranial aneurysms with larger size and size ratio exhibit increased expression of CD68 and NFKB1, which reflect acute inflammation and the activation of inflammatory pathways, respectively." (PMID 41368358, 2025). "Numbers of positively stained saccular intracranial aneurysm (sIA) samples and mean, median, and range of leukocyte densities in CD3+, CD4+, CD8+, CD20+, CD68+, and CD163+ stainings." (PMID 40498464, 2025).
juvenile xanthogranuloma (4 papers, 2017 to 2025). A benign histiocytic tumor that occurs during childhood; it is distinct from Langerhans cell histiocytosis. "Both BCH and juvenile xanthogranuloma share similar immunohistologic markers: CD68, CD163, and Factor XIIIa." (PMID 40678378, 2025). "Juvenile xanthogranuloma (JXG) is a rare non-Langerhans cell (LCH) histiocytic disorder with histologic features characteristic of dermal dendrocytes (fascin+, CD1a−, CD207−) and macrophages (CD14+, CD68+, CD163+, and factor XIIIa+)." (PMID 28512266, 2017).